BAG3 (BAG cochaperone 3)
Diseases named in the same sentence as BAG3 in open-access papers (continued):
Sharing a sentence is not in itself a finding about the gene and the disease.
glioblastoma (continued). "It is notable that our study is the first to demonstrate that single knock-down of both Bag3 and Usp9X are sufficient to sensitize glioblastoma cells to BH3-mimetics." (PMID 26008975, 2015). "Bag3 protein expression is increased in both low- and high-grade astrocytic gliomas, with the highest expression levels found in glioblastoma." (PMID 26008975, 2015). "Next we silenced Usp9X in LN229 glioblastoma cells to determine the impact of Usp9X on the chaperone Bag3 as well as initiator- and effector caspases." (PMID 26008975, 2015). "As an example, BAG3 expression in glioblastomas increases with tumor grade, and BAG3 silencing by siRNA inhibits cell growth both in vitro and in vivo, while elevated BAG3 levels in pancreatic ductal adenocarcinoma (PDAC) and medulloblastoma are associated with shorter patient survival." (PMID 40507324, 2025). "For example, the expression of BAG3 can be inhibited by polyomavirus JC (JCV), which is a human neurotropic virus, as a result of suppressed transcription of the BAG3 promoter through physical interaction with the T antigen in the infected glial cells or transfected human glioblastoma cells." (PMID 32365661, 2020). "In normal cells, BAG3 expression is very low, while its expression is higher in many neoplastic cell types including leukemias and lymphomas, solid tumors such as melanoma, glioblastoma, pancreatic carcinomas and thyroid carcinomas." (PMID 30081850, 2018). "BAG3 expression is induced by stress stimuli in normal cells types, while is constitutive in several human cancer cells (leukemia, myeloma, neuroblastoma, pancreas, colon, glioblastoma)." (PMID 29487711, 2018). "Via the stabilization of the transcription factor STAT3 (signal transducer and activator of transcription 3) overexpressed BAG3 may confer stem-cell like characteristic on glioblastoma cells." (PMID 28680391, 2017). "In contrast to all other autophago-lysosomal factors, BAG3 showed significantly stronger staining levels in low-grade pilocytic astrocytoma as well as normal appearing brain tissue and infiltration zone than in glioblastoma tumor centers." (PMID 26956048, 2016). "Moreover, TIC10/ONC201 caused a down-regulation of the Hsp70 co-chaperone Bag3, which has been reported to mediate resistance to BH3-mimetics in glioblastoma by regulating Mcl-1 levels." (PMID 26474387, 2015). "Notably, aggressive tumor subtypes, including anaplastic thyroid carcinoma and glioblastoma—which are characterized by therapy resistance and poor prognosis—demonstrate elevated BAG3 positivity, suggesting BAG3-driven mechanisms contribute to their aggressive phenotype." (PMID 41367874, 2025). "Building on our previously identified and novel deciliating function of BAG3, we further decipher the molecular mechanisms of BAG3‐regulated cilia homeostasis in glioblastoma (GBM)." (PMID 38655699, 2024). "The BAG3 expression level is usually low or barely detectable in most normal tissues (except for the cardiac and skeletal muscle tissues); however, high BAG3 expression levels are detected in many solid tumors, such as prostate cancer, ovarian cancer, and glioblastoma." (PMID 30081850, 2018). "Especially, a high constitutive BAG3 expression is reported in muscle cells (heart and skeletal) and in cells of different cancer types (e.g., lymphoid or myeloid leukemias, neuroblastomas, prostate carcinomas, ovarian and breast carcinomas, glioblastomas or pancreatic carcinomas)." (PMID 28680391, 2017). "Thus, targeting both Bag3 and Usp9X may represent novel approaches to overcome intrinsic and potentially extrinsic apoptotic resistance in glioblastoma." (PMID 26008975, 2015). "Another SOX2-associated protein BAG3 (Bcl2-associated athanogene), which was identified in our proteomic screens conducted in DAOY and U87 cells, has been reported to be overexpressed in GB, and knockdown of BAG3 in a rat model of glioblastoma sensitizes the cells to apoptosis." (PMID 23667531, 2013).
glioblastoma (continued). "In addition, BAG3 expression is increased in a large number of cancers including: acute lymphocytic and B cell chronic lymphocytic leukemia thyroid carcinoma; melanomas non-small-cell lung cancer; hepatocellular carcinoma; pancreatic adenocarcinoma, small cell carcinoma of the lung and glioblastoma." (PMID 25925243, 2015). "Our data show that treatment with GX15-070 results in a dose-dependent down-regulation of Bag3 in LN229 and T98G glioblastoma cells." (PMID 26008975, 2015). "BAG-3 may be particularly interesting to investigate given that BAG-3 physically interacts with signal transducer and activator of transcription 3 (STAT3) to stabilize STAT3 and endow some stem-like qualities in glioblastoma multiforme (GBM) cells." (PMID 37970210, 2023). "At the same time, BAG3, a non-canonical inducer of autophagy, was upregulated in reactive astrocytes, allowing to connect two distinct pathological states such as glioblastoma progression and ischemia." (PMID 33525678, 2021). "Expression of exogenous Tat, a protein expressed by the HIV virus, in glioblastoma cell lines enhances BAG3 protein but not mRNA levels." (PMID 25925243, 2015). "To address the question whether down-regulation of Bag3 by GX15-070 sensitizes glioblastoma cells towards ABT263-mediated apoptosis, we performed knock-down experiments silencing Bag3 prior to treatment with increasing concentrations of ABT263." (PMID 26008975, 2015). "BAG3 was found highly expressed, compared with normal human cells or tissue, in many solid tumors, such as HCC, nonsmall cell lung cancer, thyroid carcinoma, pancreatic cancer, glioblastoma, and colorectal carcinomas." (PMID 24895585, 2014). "In addition, HIF1α is involved in the regulation of miR-210-3p, CXCR7, CXCR4, IDH1, C-Met, SF/HGF, the S100A4/NMIIA axis, NO, VEGF, BAG3, and TDO2, and influences various aspects of the glioblastoma biology such as angiogenesis, invasion, metabolism, and therapy resistance." (PMID 38893207, 2024).
breast cancer (23 papers, 2006 to 2025). A primary or metastatic malignant neoplasm involving the breast. "In susceptible cases, the co-chaperone, anti-apoptotic BAG3 revealed a high expression in breast cancer cells that were resistant against a certain class of chemotherapy drugs." (PMID 39795972, 2024). "In breast cancer cells and in tissue from breast cancer patients, stress resistance and survival after oxidative stress were demonstrated to be linked to an ERα-induced non-canonical autophagy pathway which is, at least in part, mediated by BAG3." (PMID 28680391, 2017). "Levels of HSP70 and BAG3 proteins were also reduced after overexpression of ds-miR-570 in these breast cancer cell lines." (PMID 36114410, 2022). "Knock down of BAG3 significantly reduced the ability of GZ17-6.02 to cause autophagosome formation and to kill breast cancer cells." (PMID 35035775, 2022). "Of some significance in cancer, it has been shown that the HSP70 co-chaperone BAG3 can be targeted in mammary tumor growth." (PMID 36114410, 2022). "Nevertheless, evidence for ubiquitin–proteasome-sustained degradation of MVP was provided in the case of MCF7 breast cancer cells, wherein BAG3 interacted with and stabilized the vault nanoparticle, which also resulted in apoptosis resistance." (PMID 33572350, 2021). "Adriamycin (brand name of doxorubicin, DOX), a senescence-inducing drug, triggered BAG3 upregulation in MCF7 breast cancer cells." (PMID 33572350, 2021). "A BAG3 inhibitor showed promising efficacy in inhibiting cancer cell proliferation in breast cancer, prostate cancer, pancreatic cancer, and lung cancer cell lines." (PMID 34831344, 2021). "Collectively, the data support the notion that BAG3 is a potential therapeutic target of breast cancer." (PMID 32121220, 2020). "BAG3 is frequently overexpressed in breast cancer and high BAG3 expression levels are correlated with a poor prognosis." (PMID 32121220, 2020). "Our previous work demonstrated a role for BAG3 in regulation of the ERK signalling pathway in different breast cancer cell models." (PMID 29644001, 2018). "Patients with BAG3 high/CXCR4 high showed worse overall survival than those with BAG3 high/CXCR4 low, confirming the involvement of CXCR4 in oncogenic function of BAG3 in breast cancer." (PMID 28703799, 2017). "Taken together, this is the first study to describe a novel role of BAG3 in post-transcriptional regulation of CXCR4 via interaction with its transcript in breast cancer, by which promotes BCSC-like properties." (PMID 28703799, 2017). "Transwell invasion experiments demonstrated that ectopic BAG3 expression promoted invasion of breast cancer cells." (PMID 28703799, 2017). "The current study reported that BAG3 was induced under specific floating culture conditions that enrich breast cancer stem cell (BCSC)-like cells in spheres." (PMID 28703799, 2017). "The clonogenic potential of breast cancer cells was analyzed in limited dilution assays, which revealed that ectopic BAG3 expression increased clonogenicity compared with control cells." (PMID 28703799, 2017). "Inducible BAG3 expression appeared to be crucial for BCSCs maintenance and renewal, as BAG3 knockdown resulted in marked decreases in first-generation and second-generation mammosphere-forming activity of breast cancer cell lines." (PMID 28703799, 2017). "Even in the presence of AMD3100, breast cancer cells with BAG3 expression had higher mammosphere-forming activity compared with their control partners." (PMID 28703799, 2017). "BAG3 expression was also evaluated by immunohistochemical analysis in 144 breast cancer specimens and confirmed that BAG3 expression was significantly increased in most tumor specimens relative to peritumor tissues." (PMID 28703799, 2017). "Consistent with mRNA expression, western blot demonstrated that forced BAG3 expression increased CXCR4 protein levels in breast cancer cells." (PMID 28703799, 2017).
breast cancer (continued). "Immunoblot analysis of lysates obtained from surgical samples of 10 breast cancer patients confirmed increases of BAG3 expression in most tumors compared with corresponding peritumor tissues." (PMID 28703799, 2017). "Real-time PCR confirmed that floating culture and BAG3 overexpression increased CXCR4 mRNA levels in breast cancer cells." (PMID 28703799, 2017). "BCSC-enrichment culture demonstrated that AMD3100 significantly suppressed mammosphere-forming capacity of breast cancer cells in both control and BAG3 ectopically expressed cells." (PMID 28703799, 2017). "RNA immunoprecipitation (RIP) demonstrated that BAG3 was recruited to CXCR4 mRNA in breast cancer cells." (PMID 28703799, 2017). "We have identified that over-expression of BAG3, YAP1 and LGALS1 was associated with poor prognosis in HER2-positive breast cancers." (PMID 26883193, 2016). "In line with our recent findings, the results of a proteomic analysis revealed a role for BAG3 and Major Vault Protein as potent pro-survival factors that contribute to chemotherapy resistance in breast cancer cells." (PMID 26158518, 2015). "Increased BAG3 expression is shared across all cancer types and can create a desirable microenvironment for cancer progression in pancreatic ductal adenocarcinoma, melanomas, lung cancer, breast cancer, and prostate cancer." (PMID 34831344, 2021). "Other aspects of drug resistance were also derived from the stress protein Bcl-2-associated athanogene 3 (BAG3), which could stabilize Mcl1 expression, thus contributing to ABT-737 resistance in breast cancer and prostate cells." (PMID 34753495, 2021). "The number of mammospheres significantly decreased in breast cancer cells with BAG3 knockdown." (PMID 28703799, 2017). "In breast cancer cells it could be demonstrated that upregulated BAG3 contributes to therapy-induced senescence, thereby preventing apoptosis and mediating chemotherapy resistance." (PMID 28680391, 2017). "Given that BAG3 might regulate CXCR4 in breast cancer, real-time PCR was performed to evaluate the relationship between BAG3 and CXCR4." (PMID 28703799, 2017). "Therefore, this study establishes BAG3 as a potential adverse prognostic factor and a therapeutic target of breast cancer." (PMID 28703799, 2017). "Importantly, real-time PCR and western blot demonstrated that BAG3 expression was also increased during floating culture of breast cancer cells compared with their adhesive partners." (PMID 28703799, 2017). "Importantly, we observed a positive correlation between mammosphere-forming capacity and BAG3 expression in breast cancer cell lines." (PMID 28703799, 2017). "An unmet need exists for effective treatment strategies for anti-hormone resistant ERα breast cancer and BAG3 might represent an interesting alternative therapeutic target." (PMID 26158518, 2015). "Ninety genes belonging to the GO category of 'apoptosis', including members of the BAG family (BAG1, BAG2, BAG3), as well as members of the breast cancer 'proliferation signatures' (BUB1, PLK1, CCNE1, CCND1 and CCNB1) were also identified as up-regulated in our DTET." (PMID 17014703, 2006). "Recently, the co-chaperone Bcl-2-associated athanogene 3 (BAG3) that modulates age-related autophagic activity was shown to diminish proteotoxicity via selective autophagy and is highly expressed in estrogen receptor-positive neuroblastoma and breast cancer cells." (PMID 26158518, 2015). "Mechanistically, compound 3b exerted its antiproliferative activities against breast cancers both in Bag3-dependent (via ERK activation) and Bag3-independent ways (via suppressed Akt and c-Myc)." (PMID 36835501, 2023). "Immunohistochemical analysis confirmed that BAG3 and CXCR4 intensities were positively correlated in most breast cancer specimens." (PMID 28703799, 2017). "BAG3 was also found to be positively correlated with CXCR4 expression and unfavorable prognosis in patients with breast cancer." (PMID 28703799, 2017).
breast cancer (continued). "Real-time RT-PCR demonstrated that BAG3 knockdown decreased total CXCR4 mRNA, while nascent CXCR4 mRNA was unaltered in breast cancer cells." (PMID 28703799, 2017). "While the overexpression of anti-cell death proteins, such as BAG3, and other pathways protective against cell damage confer cancer resistance, their contribution to the outcome of CD200-targeted therapies against breast cancer remains unclear." (PMID 39795972, 2024). "In addition, BAG3 was found to be positively correlated with CXCR4 expression and unfavorable prognosis in patients with breast cancer." (PMID 28703799, 2017). "BAG3 significantly promoted BCSC-like properties as evidenced by increase in the fraction of CD44+/CD24− subpopulation, as well as a significant increase in the number and size of mammospheres derived from breast cancer cells." (PMID 28703799, 2017). "Ectopic BAG3 overexpression increased CD44+/CD24− CSC subpopulations, first-generation and second-generation mammosphere formation, indicating that BAG3 promotes CSC self-renewal and maintenance in breast cancer." (PMID 28703799, 2017).
pancreatic cancer (22 papers, 2014 to 2025). "In cancer, BAG3-dependent autophagy is strongly associated with drug resistance, and in many cancer types, such as colon and pancreatic cancer, high BAG3 expression is a poor prognostic factor." (PMID 35203329, 2022). "BAG3 is a cochaperone with multiple cellular functions and is implicated in metabolic reprogramming of pancreatic cancer cells." (PMID 31657880, 2020). "Extracellular BAG3 significantly influences the tumor microenvironment by promoting fibrosis and activating stromal cells, as demonstrated in pancreatic cancer." (PMID 40507324, 2025). "BAG3 protein has also been described as a serum biomarker in pancreatic cancer, as well as in other illnesses characterized by inflammation, such as psoriasis, and fibrosis, such as systemic sclerosis." (PMID 40507324, 2025). "In particular, Western blot analyses revealed that pancreatic cancer cell lines displayed BAG3 signals in both cell lysates and supernatants, confirming previous findings that indicated BAG3 secretion by pancreatic ductal adenocarcinoma cells." (PMID 41367874, 2025). "Mechanistically, BAG3 stabilizes hexokinase-2 mRNA which leads to increased hexokinase-2 (HK2) expression helping to promote aerobic glycolysis in pancreatic cancer cells, while BAG3 knockdown destabilizes HK2." (PMID 36980278, 2023). "In the pancreatic cancer microenvironment, two distinct mechanisms involved in supporting tumor growth and suppressing the anti-tumor immune response are mediated by BAG3/BAG3R and SIRPα/CD47 axes." (PMID 35241649, 2022). "Using univariate Cox regression, a forest map was generated showing seven ARGs associated with pancreatic cancer prognosis: BAK1, ITGA3, BIRC5, WDR45, BAG3, APOL1, and RAB24." (PMID 35488119, 2022). "The results show that fibrotic solid tumors, such as renal cell carcinoma, esophageal cancer, ovarian cancer, endometrial cancer, head and neck cancer, bladder cancer and pancreatic cancer, have a high amplification rate of bag3 gene." (PMID 34741483, 2022). "For this purpose, we studied the effects of an anti-BAG3 and an anti-SIRPα antibody, separately or in combination, in a murine model of pancreatic cancer orthotopic allografts in syngeneic immunocompetent animals." (PMID 35241649, 2022). "In several pancreatic cancer murine models, BAG3 blockade by a monoclonal antibody impairs the activation of TAMs and CAFs." (PMID 35241649, 2022). "The BAG3- and SIRPα- mediated pathways trigger distinct cellular targets and signaling mechanisms in pancreatic cancer microenvironment." (PMID 35241649, 2022). "We previously reported that treatment of pancreatic cancer heterotopic allografts with anti-BAG3 antibody down-modulated CAF activation and impaired the desmoplastic structure in pancreatic cancer stroma." (PMID 35241649, 2022). "In this sense, it is noteworthy that an anti-BAG3 antibody is able to sensitize pancreatic carcinoma to the effect of an anti-PD-1 antibody." (PMID 35241649, 2022). "Basal BAG3 expression was found to be elevated in many cancer entities, e.g., in lymphocytic leukemia, neuroblastoma, glioma, thyroid, breast, and pancreatic cancer." (PMID 32121220, 2020). "Based on these results, secreted BAG3 (and its receptor IFITM-2) represent potential clinical candidate molecules for the treatment of pancreatic cancer (development of an anti-BAG3 humanized antibody for treatment of pancreatic cancer)." (PMID 32121220, 2020). "In conclusion, the current study demonstrated that BAG3 expressed in PSCs maintains their own activation and promotes migration and invasion of pancreatic cancer cells via autocrine and paracrine respectively." (PMID 31119886, 2019). "On the other hand, BAG3‐positive PSCs also facilitate migration and invasion of nearby pancreatic cancer cells via secretion of soluble protein factors including IL‐8, MCP1, TGF‐β2 and IGFBP2." (PMID 31119886, 2019).